GDF15 (growth differentiation factor 15)
Diseases named in the same sentence as GDF15 in open-access papers (continued):
Sharing a sentence is not in itself a finding about the gene and the disease.
prostate carcinoma (continued). "For example, the high expression of GDF15 inhibited the metastasis of lung adenocarcinoma via regulation of the TGF‐β/Smad signaling pathway, and GDF15 plays a vital role in the mediation of proliferation and apoptosis of prostate cancer cells." (PMID 33098235, 2020). "GDF15 not only promoted bone metastasis of prostate cancer but also induced colon cancer formation in senescence-associated tissue microenvironment." (PMID 33123476, 2020). "Hypoxia and anoxia also increase GDF15 expression in retinal pigment epithelial cells, colon cancer, prostate cancer, and glioblastoma." (PMID 33120884, 2020). "In prostate cancer, GDF-15 serum levels independently predicted lower cancer-specific survival with an adjusted HR of 2.98 (95% CI: 1.82–4.68)." (PMID 32508832, 2020). "Since most, if not all, of these pathways have been implicated in prostate cancer progression, suppressing the activities of these pathways by inducing GDF15 is consistent with the antitumor effect of MSA in prostate cancer." (PMID 31539407, 2019). "Consistently, we found that TGF-β signaling is negatively correlated with GDF15 levels in clinical prostate cancer samples." (PMID 31539407, 2019). "Since most, if not all, of these pathways have been implicated in prostate cancer progression, suppressing their activities by inducing GDF15 is consistent with the anticancer effects of MSA in prostate cancer." (PMID 31539407, 2019). "Overall, this study provides support for GDF15 as an immediate target of MSA in prostate cancer cells." (PMID 31539407, 2019). "To assess the prognostic value of GDF15 expression in primary prostate cancer, we analyzed the Erho microarray dataset, which contains 545 radical prostatectomy samples with a median follow-up of 16.9 years, for association with clinicopathologic parameters." (PMID 31539407, 2019). "Similar to the role of TGF-β in cancer development and progression, both tumor-suppressing and tumor-promoting functions of GDF15 have been reported in different cancer types, including prostate cancer." (PMID 31539407, 2019). "Together, the association between lower GDF15 expression and worse clinical outcome supports a role of GDF15 downregulation in prostate cancer progression." (PMID 31539407, 2019). "In summary, the work described herein demonstrates that GDF15 is an immediate target of MSA in prostate cancer cells and that GDF15 induction contributes to MSA inhibition of cell proliferation and induction of apoptosis." (PMID 31539407, 2019). "Here, using multiple preclinical prostate cancer models, we demonstrated in vitro and in vivo that GDF15 is a most highly induced, immediate target of MSA." (PMID 31539407, 2019). "Here, we showed that GDF15 is one of the most highly induced genes by MSA in multiple preclinical prostate cancer models in vitro and in vivo and that the induction occurred rapidly." (PMID 31539407, 2019). "This seems likely as both mechanical forces induce cytoskeletal alterations, which were already shown to result in enhanced GDF15 expression in LNCaP prostate carcinoma cells." (PMID 31395909, 2019). "Ectopic expression of GDF15 has been shown to decrease cell growth and induce apoptosis in some prostate cancer cell models but increase cell growth and metastatic potential in some other models or other conditions." (PMID 31539407, 2019). "To assess the clinical relevance of increased GDF15 expression in prostate cancer, we examined a number of published cohorts for GDF15 expression." (PMID 31539407, 2019). "GDF15 transgenic mice were also crossed with the Transgenic Adenocarcinoma of Mouse Prostate (TRAMP) transgenic model of spontaneous prostate cancer." (PMID 30542297, 2018).
prostate carcinoma (continued). "Consistently, GDF15 was reported to be highly expressed in prostate cancer, malignant melanoma, ovarian cancer and pancreatic ductal adenocarcinoma." (PMID 29636108, 2018). "In various tumors, including prostate cancer, GDF15 interacts with the extracellular matrix and promotes tumor progression and metastasis." (PMID 30090875, 2018). "Studies have shown that GDF15 promotes cell proliferation and tumor formation in ovarian cancer, pancreatic ductal adenocarcinoma and prostate cancer." (PMID 29636108, 2018). "GDF15 concentration was elevated in prostate cancer patients and correlated with the progression of cancer." (PMID 30542297, 2018). "GDF-15 is overexpressed in numerous types of tumors such as colon cancer, prostate cancer, pancreatic cancer, breast cancer, and thyroid carcinomas." (PMID 28489602, 2017). "GDF15 promoted metastasis through the FAK-RhoA signaling pathway in prostate cancer, whereas this metastatic function was achieved through Smad2/3 signaling in colorectal cancer." (PMID 27903972, 2017). "Actually, serum GDF-15 levels are often increased in patients suffering from different types of cancer, including ovarian cancer, pancreatic cancer, and prostate cancer." (PMID 28489602, 2017). "To investigate its effect on PCa development and spread, we have used TRAMP prostate cancer prone mice bearing a germline deletion of MIC-1/GDF15 (TRAMPMIC-/-)." (PMID 25695521, 2015). "More recently we have assessed the effect of MIC-1/GDF15 overexpression on the course of cancer in Transgenic Adenocarcinoma of Mouse Prostate (TRAMP) prostate cancer prone transgenic mice." (PMID 25695521, 2015). "Genes typically associated with prostate cancer are evident: PCA3 and GDF15 levels are elevated, and TP63 and MSMB levels are reduced across all tumour subgroups, and are not subtype-specific." (PMID 26501111, 2015). "The GDF-15 level is also elevated in several cancers including prostate cancer, ovarian cancer, pancreatic cancer, colorectal cancer, and multiple myeloma." (PMID 24312445, 2013). "To directly assess the impact of MIC-1/GDF15 on prostate cancer growth, we assigned 60 TRAMP and 60 TRAMPfmsmic-1 mice at 4–6 weeks of age and culled them progressively throughout 8–33 weeks of age." (PMID 22952779, 2012). "So far, a variety of GDF15 biological functions has been reported, such as an anti-apoptotic in cardiomyocytes, metastasis in prostate cancer cells, motoneuron development, osteoclast differentiation, iron overloading and erythropoiesis." (PMID 21625435, 2011). "However, CD10, KHDRBS3, PCLAF, PSMA, SIK2 and GDF15 were differentially expressed with prostate cancer progression." (PMID 39578642, 2025). "Previous studies indicated that GDF15 from prostate cancer cells (PCa) stimulates bone marrow mesenchymal stem cells to differentiate into osteoblasts and enhances CCL2 expression, which attracts the tumour to bone surfaces and contributes to PCa bone metastasis." (PMID 40292733, 2025). "Furthermore, GDF-15-mediated chemotherapy resistance has been reported for docetaxel and oxaliplatin in prostate cancer and CRC, respectively." (PMID 41294666, 2025). "The alterations of GDF family genes, especially GDF15 (macrophage inhibitory cytokine-1), have been observed to be correlated with various types of tumors including breast cancer, colorectal cancer, gastric cancer (GC), glioma, and prostate cancer." (PMID 40153751, 2025). "By contrast, calcitriol increased GDF15 expression in human prostate cancer cells." (PMID 38732029, 2024). "Notably, GDF15 was associated with 16 of 18 diseases studied, whereas ACRV1 (a testis-specific protein involved in spermatogenesis) was only associated with prostate cancer." (PMID 39117878, 2024). "Furthermore, enhanced osteoblast differentiation was also reported in prostate cancer cells when transfected with GDF15 cDNA." (PMID 38392243, 2024).
prostate carcinoma (continued). "They found that prostate cancer cells highly express and secrete GDF-15, which further induces the expression of osteoclastogenesis-related genes in osteoclasts and the expression of chemoattractant protein-1 (MCP-1/CCL2), which is involved in macrophage recruitment to osteoblasts in mice." (PMID 39000420, 2024). "Moreover, GDF15-expressing fibroblasts were shown to exert systemic effects on the outgrowth of distant, otherwise indolent, prostate cancer cells." (PMID 37222464, 2023). "Osteocytes produce GDF15, which supports prostate cancer migration and invasion." (PMID 37174109, 2023). "Thus, the GDF15 level has recently been suggested as a predictive biomarker for recurrence and survival in colorectal cancer and prostate cancer." (PMID 36769245, 2023). "Moreover, transfection with GDF15 cDNA was shown to promote osteoblast differentiation in prostate cancer cells in vitro." (PMID 37373159, 2023). "PCa patients with high GDF15 expression have poor survival rate at the late stage of disease progression, which indicates GDF15, especially the corresponding glycol-modified form, may be a prognostic marker for late-stage prostate cancer." (PMID 35853851, 2022). "In addition, prostate cancer cells induced osteocytes to secrete GDF15 into the bone microenvironment which, in turn, stimulated early growth response 1 (EGR1) expression in prostate cancer cells and promoted tumor progression." (PMID 35994202, 2022). "Our data suggest the importance of N70 glycosylation in regulating GDF15 function and may explain the controversial role of GDF15 in prostate cancer." (PMID 35853851, 2022). "GDF15 is reported to promote the growth of ovarian and prostate cancers." (PMID 35280749, 2022). "Moreover, in prostate cancer cells, the upregulation of GDF-15 was directly affected by the downregulation of T and E2." (PMID 34942914, 2021). "Furthermore, another study also showed that EGR1 acts as a key regulator of prostate cancer through the suppression of GDF15." (PMID 34681812, 2021). "Moreover, the circulating levels of GDF15 are elevated in several cancers, including endometrial cancer, prostate cancer, pancreatic cancer, and colorectal cancer." (PMID 32076610, 2020). "Likewise, gene expression data from The Cancer Genome Atlas (TCGA) database show highest GDF-15 levels in prostate cancer and reveal also mRNA overexpression in breast, liver, colorectal, cervical, renal cell, hepato-, and cholangiocellular carcinomas." (PMID 32508832, 2020). "The overall MIC-1/GDF15 was elevated in prostate cancer compared to benign controls." (PMID 33081054, 2020). "Perceiving GDF-15 as an anti-inflammatory molecule in cancer may then also explain paradoxical findings of GDF-15 overexpression on prostate cancer development and spread." (PMID 32508832, 2020). "We investigated the role of immunity in GDF15 induced reduction in prostate cancer (PCa) growth." (PMID 32502202, 2020). "Consequently, the role of GDF15 in mediating the growth-suppressive effects of MSA is likely to be specific to prostate cancer cells that are at an advanced stage." (PMID 31539407, 2019). "The seemingly paradoxical role of GDF-15 in prostate cancer might be attributed to the biphasic regulation of GDF15 expression in early-stage of tumor development versus during tumor progression." (PMID 31539407, 2019). "On the other hand, testosterone might directly regulate the expression and secretion of GDF-15 in prostate cancer cells." (PMID 30819257, 2019). "The observation that a correlation exists in patients with prostate cancer between the magnitude of their weight loss and the levels of circulating GDF15 but not IL6 strongly suggested this relationship translates to humans." (PMID 30542297, 2018). "Furthermore, it was reported that GDF-15 protects prostate cancer and colon cancer cells from the deleterious effects of chemotherapeutic agents." (PMID 26741507, 2016).
prostate carcinoma (continued). "In a study evaluating gene expression changes in prostate cancer samples pre- and post docetaxel/mitoxantrone treatment, GDF-15 was one of highest up-regulated genes post-treatment, illustrating that cytostatics can influence GDF-15 expression in both malignant and non-malignant cells." (PMID 25590623, 2015). "Furthermore, the link between GDF-15 and weight regulation was suggested when it was found that elevated bloodstream levels of GDF-15 were associated with weight loss in individuals with advanced prostate cancer." (PMID 39456699, 2024). "By contrast, the only biomarkers associated with breast cancer risk were NT-proBNP and HbA1C, whereas only GDF-15 (negative) and NT-proBNP (positive) were associated with prostate cancer, only GDF-15 and HbA1C with lung cancer risk, and only NT-proBNP with colorectal cancer risk." (PMID 34935094, 2022). "Previous studies indicate that activated PERK-eIF2α signaling could drive the expression of GDF15, which is discovered as an important mediator in promoting cell growth of prostate cancer and EMT of CRC cells in vitro, and even acts as a driver in cachexia progression." (PMID 32076610, 2020). "A polymorphism (H6D) in the GDF15 gene manifests as a non-conservative amino acid change in the sequence of the mature domain of GDF15 and alters the risk and behavior of colorectal and prostate cancers." (PMID 32502202, 2020). "Therefore, the role of GDF15 in prostate cancer is likely to be stage specific." (PMID 31539407, 2019). "The diagnosis efficiency of GDF15 could be comparable to CA19‐9 in prostate cancer." (PMID 26990020, 2016). "More importantly, some top genes, such as GDF15, are involved in the TGF-β signalling pathway, which has been reported to be involved in prostate cancer metastasis, suggesting an increased invasive and metastatic capability of tumour cells at this stage." (PMID 40167331, 2025). "However, whether GDF15 acts as a suppressor or promoter in prostate cancer remains unresolved." (PMID 35853851, 2022). "Endoplasmic reticulum (ER) stress has also been shown to increase GDF15 expression, and MSA is known to induce ER stress in prostate cancer cells." (PMID 31539407, 2019). "Down-regulation of miR-34a/b/c suppressed tumor formation in colorectal cancer, while over-expression of miR-34a in aggressive prostate cancers (PCAs) cells reduced proliferation and colony formation by CtBP1\miR-34a\STMN1\GDF15 pathway." (PMID 30319976, 2018). "In order to obtain the most reliable data on the overall role of MIC-1/GDF15 in the biology of PCa, and by analogy cancer in general, we utilised Transgenic Adenocarcinoma of Mouse Prostate (TRAMP) prostate cancer prone mice." (PMID 22952779, 2012). "In prostate cancer patients, serum MIC-1/GDF15 concentrations independently predict bone metastasis and overall survival." (PMID 22952779, 2012). "Plasma levels of GDF15 have been studied as a biomarker in cardiovascular disease and elevated levels have been seen in metastatic CRC, breast and prostate carcinomas compared with normal controls." (PMID 21468045, 2011). "Indeed, a recent study reports that the propeptide domain of pro-NAG-1/GDF15, which remains after the cleavage of mature NAG-1/GDF15, promotes proliferation, invasion, and migration in prostate cancer cell lines when administered as a treatment." (PMID 40316530, 2025). "While it will be of interest to utilize genetically engineered models with GDF15 or the receptors knock out in tumors or stromal compartments, currently available prostate cancer models do not spontaneously metastasize to bone at high frequency." (PMID 35058441, 2022). "Several studies have shown that GDF15 can induce PI3K/Akt and Erk1/2 activation in esophageal squamous cell carcinomas, breast, cervical, gastric, and prostate cancers, while in brain tumors it was only found that an overexpression of GDF15 did not affected Erk1/2 activation." (PMID 31612114, 2019).
prostate carcinoma (continued). "On the other hand, both tissue and serum levels of GDF15 have been shown to be elevated in prostate cancer patients relative to non-cancerous individuals." (PMID 31539407, 2019). "Several studies have shown that GDF15 can induce PI3K/Akt and Erk1/2 activation in esophageal squamous cell carcinomas, breast, cervical, gastric and prostate cancers, while regarding brain tumors it was found that an overexpression of GDF15 in brain cancer cells did not affected Erk1/2 activation." (PMID 31612114, 2019). "Growth differentiation factor 15 (GDF15) is a member of the TGF-β superfamily, and evidence suggests that a substantial amount of GDF15 is secreted in various human cancers, such as ovarian cancer, prostate cancer, and breast cancer, among others." (PMID 29636108, 2018). "In a retrospective study, GDF15 serum level was determined in 70 samples from prostate cancer patients and normal and biopsy-negative individuals." (PMID 30542297, 2018). "GDF15 also activates focal adhesion kinase (FAK) signaling, driving prostate cancer metastasis." (PMID 29212236, 2017). "GDF15 could promote human prostate cancer cells metastasis through FAK-RhoA pathway, however we found that GDF15 could promote colorectal cacner metastasis through activating EMT process." (PMID 26497212, 2016). "Recently, GDF15 have been considered as a negative prognostic biomarker in colorectal cancer, gastric cancer, oral squamous cell carcinoma and prostate cancer." (PMID 26497212, 2016). "Overexpression of EGR1, GDF15 and MYC in prostate cancer was previously reported in the literature." (PMID 28005952, 2016). "Our study reveals a novel regulatory mechanism of prostate cancer AR inhibitor resistance, raises the possibility of AR/SRC dual-targeting of castration-resistance of prostate cancer, and lays foundation for the future development of selective inhibitors of GDF15 glycosylation." (PMID 35853851, 2022). "Similarly, MIC-1/GDF15 is regulated by the inflammatory cytokines and clinical evidence supports the notion that serum MIC-1/GDF-15, in combination with PSA, might improve the specificity for prostate cancer detection." (PMID 27429614, 2016). "Unlike in prostate cancer cell lines, we observed that in colorectal cancer cell lysates, only pro-NAG-1/GDF15 is highly expressed, with little to no detection of mature NAG-1/GDF15." (PMID 40316530, 2025).